HOXB1 (homeobox B1)
Description:
Sequence-specific transcription factor which is part of a developmental regulatory system that provides cells with specific positional identities on the anterior-posterior axis. Acts on the anterior body structures.
Synonyms: HOX2I; HCFP3; HOX2; Hox-2.9
Tractability: No criterion of Open Targets' tractability assessment is met for any kind of drug.
Gene: Protein-coding gene on chromosome 17 (48,528,526 to 48,531,011, reverse strand). Ensembl gene ENSG00000120094.
Subcellular location: Nucleus
Subcellular location (Human Protein Atlas): Nucleoplasm
Pathways (Reactome):
Developmental Biology: Activation of anterior HOX genes in hindbrain development during early embryogenesis
Gene Ontology:
Molecular function: DNA binding; DNA-binding transcription activator activity, RNA polymerase II-specific; protein domain specific binding; RNA polymerase II cis-regulatory region sequence-specific DNA binding; RNA polymerase II transcription regulatory region sequence-specific DNA binding; sequence-specific double-stranded DNA binding; DNA-binding transcription factor activity, RNA polymerase II-specific; DNA-binding transcription factor activity; sequence-specific DNA binding
Biological process: positive regulation of transcription by RNA polymerase II; pattern specification process; regulation of DNA-templated transcription; regulation of transcription by RNA polymerase II
Cellular component: nucleoplasm; chromatin; nucleus
Genetic constraint (gnomAD): Loss-of-function variants: 13 observed, 27.61 expected, observed/expected ratio (o/e) 0.47, 90% interval 0.31 to 0.75. The upper end of that interval is the gene's LOEUF score, 0.75, which puts it in group 3 of 6, group 1 being the genes least tolerant of losing a copy. Missense variants: 366 observed, 409.34 expected, observed/expected ratio (o/e) 0.89, 90% interval 0.82 to 0.98. Synonymous variants: 168 observed, 171.07 expected, observed/expected ratio (o/e) 0.98, 90% interval 0.87 to 1.12.
Homologues: Orthologues: chimpanzee HOXB1 (99% identical), macaque HOXB1 (98% identical), dog HOXB1 (92% identical), pig HOXB1 (91% identical), rabbit HOXB1 (87% identical), rat Hoxb1 (86% identical), mouse Hoxb1 (86% identical), guinea pig HOXB1 (84% identical), tropical clawed frog hoxb1 (54% identical), zebrafish hoxb1b (34% identical). Paralogues in human: HOXA1 (46% identical), HOXD1 (34% identical), HOXA4 (24% identical), HOXA3 (23% identical), HOXB3 (23% identical), HOXD3 (23% identical), HOXB2 (22% identical), HOXB4 (22% identical), HOXD4 (22% identical), PDX1 (22% identical), HOXA2 (22% identical), HOXA7 (21% identical), and 30 more.
Diseases named in the same sentence as HOXB1 in open-access papers:
HOXB1 is named in the same sentence as 39 diseases in open-access papers, as found by Europe PMC text mining. Sharing a sentence is not in itself a finding about the gene and the disease. The quoted sentences say what the papers report.
glioma (6 papers, 2015 to 2022). A benign or malignant brain and spinal cord tumor that arises from glial cells (astrocytes, oligodendrocytes, ependymal cells). "It was reported that the abnormal expression of HOXB1 was associated with the onset and development of glioma." (PMID 35254502, 2022). "Based on the clinical features of our patients, this study provides significant evidence that the downregulation of HOXB1 is associated with worse survival and that the level of HOXB1 expression is an independent predictor of prognosis in glioma patients." (PMID 26565624, 2015). "However, glioma grade (HR 2.975, P = 0.001, 95% CI 1.702–5.201), and HOXB1 expression (HR 0.111, P = 0.001, 95% CI 0.032–0.389) were associated with the progression of glioma." (PMID 26565624, 2015). "Univariate Cox regression models showed that only HOXB1 expression (hazards ratio [HR] 0.055, P = 0.004, 95% confidence interval [95% CI] 0.008–0.394) was associated with worse survival in this prospective cohort of glioma patients." (PMID 26565624, 2015). "The HOXB1 expression levels in the glioma cell lines were significantly reduced after transfection with the miR-3175 mimic, and increased after transfection with the miR-3175 inhibitor." (PMID 26565624, 2015). "In this study, we suggest that HOXB1 functions as a tumor suppressor gene in glioma and that the expression of HOXB1 is regulated by miR-3175." (PMID 26565624, 2015). "A cotransfection analysis was performed to verify that the tumorigenesis induced by the reduced expression of HOXB1 in glioma is regulated by miR-3175." (PMID 26565624, 2015). "To investigate the effects of HOXB1 on glioma cell proliferation, invasion, and apoptosis, we used the most efficient siRNA (si-HOXB1-2) for the targeted knockdown of HOXB1 expression in glioma cell lines." (PMID 26565624, 2015). "The oncogenicity induced by low HOXB1 expression was prevented by an miR-3175 inhibitor in glioma cells." (PMID 26565624, 2015). "In the Cox regression analysis, the low expression level of HOXB1 was an independent predictor of poor prognosis in glioma patients." (PMID 26565624, 2015). "The extent of wound was healing was greater in glioma cells transfected with si-HOXB1 than in those transfected with si-NC in the scratch wound assay." (PMID 26565624, 2015). "A multivariate analysis showed that HOXB1 expression (HR 0.030, P = 0.001, 95% CI 0.004–0.261) and glioma grade (HR 4.682, P = 0.021, 95% CI 1.257–17.439) were associated with shorter survival." (PMID 26565624, 2015). "We investigated the activity and molecular mechanism of HOXB1 in modulating the pathogenesis of glioma." (PMID 26565624, 2015). "We analyzed and summarized the HOXB1 expression in whole-gene profiles of human glioma tissues from two independent gene expression data sets, CGGA and GEO." (PMID 26565624, 2015). "The downregulation of HOXB1 expression promotes glioma cell proliferation and invasion and inhibits cell apoptosis." (PMID 26565624, 2015). "A preliminary bioinformatics analysis showed that HOXB1 is ectopically expressed in glioma, and that HOXB1 is a possible target of miR-3175." (PMID 26565624, 2015). "The results demonstrated that HOXB1 expression was markedly lower in glioma tissues than in control tissues." (PMID 26565624, 2015). "In this study, we determined HOXB1 expression in 40 glioma tissues and three glioma cell lines, and showed that HOXB1 expression is significantly downregulated in glioma compared with its expression in the corresponding controls." (PMID 26565624, 2015). "The variables glioma grade (HR 2.732, P = 0.001, 95% CI 1.544–5.833) and HOXB1 expression (HR 0.126, P = 0.004, 95% CI 0.031–0.511) were associated with PFS." (PMID 26565624, 2015). "Although much remains to be investigated regarding the role of HOXB1 in the pathogenesis of glioma, as a novel biomarker, HOXB1 represents a potential target for the diagnosis and treatment of glioma." (PMID 26565624, 2015).
glioma (continued). "The effect of HOXB1 on the invasiveness of glioma cells was investigated with scratch wound and Transwell assays." (PMID 26565624, 2015). "Reduced HOXB1 expression promoted the proliferation and invasion of glioma cells, and inhibited their apoptosis in vitro, and the downregulation of HOXB1 was also associated with worse survival in glioma patients." (PMID 26565624, 2015). "The relationships between the HOX genes and glioma have been investigated for a long time, but the expression and function of HOXB1 in glioma are still unclear." (PMID 26565624, 2015). "In the Transwell assay, the number of invasive glioma cells increased significantly after they were transfected with si-HOXB1 compared with those transfected with si-NC." (PMID 26565624, 2015). "In this study, we investigated the function of HOXB1 and the relationship between HOXB1 and miR-3175 in glioma." (PMID 26565624, 2015). "The oncogenicity induced by the downregulated expression of HOXB1 in glioma involves the promotion of cell proliferation, enhanced cell invasion, and the inhibition of apoptosis in vitro." (PMID 26565624, 2015). "We also observed that HOXB1 expression was significantly lower in high-grade glioma tissues (HGG; WHO III and WHO IV) than in low-grade glioma tissues (LGG; WHO I and WHO II) (CGGA)." (PMID 26565624, 2015). "HOXB1 is an anti-tumor gene acting by inhibiting the expression of survival oncogenic genes; its decreased expression had been correlated with cell invasion and proliferation and inhibited apoptosis in glioma." (PMID 34262872, 2021). "Also, accumulating studies showed that HOXB1 acted as a significant tumor suppression gene in many malignant tumors including osteosarcoma, glioma, and lung cancer." (PMID 34488545, 2021). "Han and coworkers revealed that HOXB1 acted as a tumor suppressor supervised by miR-3175 in glioma." (PMID 34488545, 2021). "However, the functional role of HOXB1 and the mechanism regulating HOXB1 expression in glioma are not fully understood." (PMID 26565624, 2015). "We investigate whether the expression of HOXB1 is also regulated by miRNAs, and whether the tumorigenic role of HOXB1 is affected by miRNAs in glioma." (PMID 26565624, 2015). "In conclusion, our data suggest that HOXB1 is a tumor suppressor gene in glioma." (PMID 26565624, 2015). "An miR-3175 mimic downregulated HOXB1 expression and an miR-3175 inhibitor upregulated it, demonstrating that the expression of both HOXB1 mRNA and HOXB1 protein are significantly regulated by miR-3175 in glioma cell lines." (PMID 26565624, 2015). "We show that HOXB1 expression is significantly downregulated in glioma tissues and cell lines, and that its expression may be closely associated with the degree of malignancy." (PMID 26565624, 2015). "Cell proliferation and apoptosis assays were performed to clarify whether the oncogenicity induced by low HOXB1 expression was affected by miR-3175 in glioma, after cells were cotransfected with si-HOXB1, the miR-3175 inhibitor, or the corresponding NCs." (PMID 26565624, 2015). "The expression of HOXB1 was lower in the glioma cells than in the control HA1800 cells." (PMID 26565624, 2015). "Our results suggest that HOXB1 functions as a tumor suppressor, regulated by miR-3175 in glioma." (PMID 26565624, 2015). "The results showed that the miR-3175 inhibitor significantly prevented the increased cell proliferation and suppressed the apoptosis induced by low HOXB1 expression, indicating strongly that miR-3175 is a critical participant in the tumor-suppressor activity of HOXB1 in glioma." (PMID 26565624, 2015). "HOXB1 expression was also examined in glioma cell lines (A172, U251 and U87)." (PMID 26565624, 2015).
glioma (continued). "Therefore, this study of the molecular mechanism of HOXB1 function in glioma should significantly improve the diagnosis and treatment of this malignancy." (PMID 26565624, 2015). "Therefore, in this study, we first investigated whether the expression of HOXB1 is abnormal in glioma, whether it correlates with patient survival, and the function of HOXB1 in oncogenesis." (PMID 26565624, 2015). "Our knowledge of the mechanism that regulates HOXB1 in cancer has predominantly involved the three-amino-acid-loop-extension (TALE) homeodomain factors that act synergistically with HOX, and it was unclear whether upstream miRNAs regulate HOXB1 expression in glioma." (PMID 26565624, 2015). "We evaluated the prognostic value of HOXB1 expression for patient OS and PFS based on the follow-up data of glioma patients." (PMID 26565624, 2015). "At H3K4me3‐depleted TSS, DNA methylation was spread along the entire CGI/promoter, possibly contributing to HOXB1 lack of expression in glioma, for instance." (PMID 33720519, 2021). "We found that HOXB1 expression differed significantly between the glioma tissues and nontumor brain tissues, in that HOXB1 expression was obviously lower in the gliomas (GSE4290)." (PMID 26565624, 2015). "The results also demonstrated that HOXB1 mRNA expression levels were not visibly different between LGG and HGG in 40 glioma tissues (P = 0.069), but the immunohistochemical analyses showed that HOXB1 protein expression levels were clearly downregulated in HGG." (PMID 26565624, 2015). "For instance, the CGI/promoters of HOXB1 and HOXC12, two genes that were not expressed in glioma samples, were marked by a combination of H3K27me3‐only and DNA methylation." (PMID 33720519, 2021). "Moreover, several of them (e.g., HOXA1, A5, A6, A7, A10, D9, and D10) were expressed in most IDHwt glioma samples, constituting thus the core HOX signature in IDHwt samples, whereas HOXB1, HOXC12, HOTTIP, and HOXB‐AS4 were not reactivated." (PMID 33720519, 2021).
pancreatic cancer (4 papers, 2012 to 2025). "In PDAC, aberrant expression of several HOX transcription factors has been described and functional studies have shown that HOXA10, HOXB7, and HOXC11 promote pancreatic cancer development while HOXA1, HOXB1, and HOXB3 act as tumor-suppressors." (PMID 40619489, 2025). "The overexpression of miRNA-10a has been observed to down-regulate the transcriptional suppressors and metastatic factors (homeobox transcription factors)—HOX (HOXB1, HOXB2, HOXA1) in various pancreatic cancer cell lines including, PANC-1, CAPAN-1, SUIT-2, KP-2 and MIA PaCa-2." (PMID 39200178, 2024). "HOXB1, which is downregulated in poor prognosis MCC, is a highly conserved transcription factor that plays an important role in morphogenesis and has been shown to be involved the metastatic potential of pancreatic cancer." (PMID 24634783, 2014).
breast carcinoma (3 papers, 2015 to 2017). "In a study on breast cancer, the sensitivity of breast cancer cell lines to killing by HXR9 was shown to be strongly associated with the combined expression of HOX genes HOXB1 through to HOXB9." (PMID 28423659, 2017). "Neither of these markers has been validated in primary tumours, although in breast cancer and mesothelioma a subgroup of primary tumours was identified that showed a very high level of the combined HOXB1-9 expression and a high HOX oncogenic to tumour suppressor ratio, respectively." (PMID 28423659, 2017). "The HOXB1-regulated expression of COL5A2, which is involved in the focal adhesion pathway, correlates with the carcinogenesis of endometrial cancer, and HOXB1 also regulates HXR9, which causes the apoptosis of breast cancer cells." (PMID 26565624, 2015). "In a study on breast cancer, the sensitivity of breast cancer cell to killing by HXR9 was shown to be strongly related to the expression of HOXB1 through to HOXB9." (PMID 28808656, 2017).
embryonal carcinoma (3 papers, 2009 to 2021). A non-seminomatous malignant germ cell tumor characterized by the presence of large germ cells with abundant cytoplasm resembling epithelial cells, geographic necrosis, high mitotic activity, and pseudoglandular and pseudopapillary structures formation. "HDAC inhibitors, including VPA, have been shown to alter Hox gene expression in mouse embryos, ES cells and human embryonal carcinoma cells and can increase levels of H3 acetylation at Hoxb1 control elements in mouse ES cells." (PMID 19564914, 2009).
lung carcinoma (3 papers, 2016 to 2021). "HOXB1 was described down-regulated in lung cancer tissue and, similarly, we found the DMR close to this gene was hypermethylated." (PMID 34262872, 2021). "HOXB1 is also regulated by hsa-let-7 g in inhibiting proliferation of lung cancer cells." (PMID 34488545, 2021).
acute myeloid leukemia (2 papers, 2013 to 2021). Acute myeloid leukemia (AML) is a group of neoplasms arising from precursor cells committed to the myeloid cell-line differentiation. "Among the HOXB cluster, HOXB1 was silent in a number of analyzed acute myeloid leukemia (AML) primary cells and cell lines, whereas it was expressed in normal terminally differentiated peripheral blood cells." (PMID 24148231, 2013). "We evaluated the endogenous expression of HOXB1 in a panel of representative primary acute myeloid leukemia (AML) cells, staged from M1 to M6, and some stabilized leukemic cell lines (U937, HL60, AML193, NB4, K562, CEM and PEER)." (PMID 24148231, 2013).
alcoholism (2 papers, 2021 to 2023). "We observed the most significant associations with alcoholism and systemic lupus erythematosus, as previously observed for the HOXB1 transcription factor." (PMID 36598580, 2023). "In contrast, the group 1 peaks, where HOXB1 and PBX1 display co-occupancy, associate with genes required in cancer and alcoholism, while the group 2 regions with co-binding of HOXB1 and REST associate with genes required in neurogenesis, neuronal processes, and behavior." (PMID 33546292, 2021).
autism spectrum disorder (2 papers, 2010 to 2011). A spectrum of developmental disorders that includes autism, and Asperger syndrome. "HOXA1 and HOXB1 have been strongly posed as candidate genes for autism spectrum disorders (ASD) given their important role in the development of hindbrain." (PMID 21980499, 2011).
endometrial cancer (2 papers, 2015 to 2019). Primary or metastatic malignant neoplasm involving the endometrium (mucous membrane that lines the endometrial cavity). "Six HiChIP target genes (BRAP, RASGRP1, HOXB1, HOXB6, HOXB7 and HOXB8) were enriched for miRNA targets of MIR196A1, itself a HiChIP target gene, providing evidence to link these genes together in a potential network that may mediate the effects of endometrial cancer risk variation." (PMID 31561579, 2019).
osteosarcoma (2 papers, 2020 to 2021). A usually aggressive malignant bone-forming mesenchymal neoplasm, predominantly affecting adolescents and young adults. "However, in osteosarcoma, patients with higher expression of let-7g displayed a poorer prognosis and lower survival rate, and the overexpression of let-7g promoted the occurrence of osteosarcoma by down-regulating HOXB1 and activating the NFkB pathway." (PMID 34572067, 2021).
Strabismus (2 papers, 2013 to 2021). A misalignment of the eyes so that the visual axes deviate from bifoveal fixation. "Moreover, the clinical observations made in our proband partially correspond with those described in patients harboring the homozygous HOXB1 c.619C > T mutation: the phenotype included bilateral facial palsy, hearing loss, and strabismus." (PMID 23419067, 2013). "CFP with or without strabismus, but without a limitation in horizontal or vertical ocular movement and without other major systemic involvement is suggestive of HCFP and includes the HOXB1 syndrome as well as genetically undefined forms of autosomal dominant CFP (HCFP1, HCFP2)." (PMID 33827624, 2021).
anencephaly (1 paper, 2019). A rare neural tube defect during pregnancy, resulting in the absence of a large portion of the brain and skull in the fetus. "To investigate the potential effect of expression levels of the selected HOX genes (HOXA1, HOXA7, HOXA9, HOXA10, HOXB1, and HOXB7) in anencephaly, we evaluated 10 anencephaly cranial tissues and 10 matched normal fetus cranial samples by the NanoString technique." (PMID 30992047, 2019).
Anxiety (1 paper, 2015). Intense feelings of nervousness, tension, or panic often arise in response to interpersonal stresses. "Thus, the difference in unsupported rearing of Hoxb1-null mice cannot be attributed to perturbed emotional processing (e.g., higher anxiety, motivating them to stay away from the most open area of the arena and close to the walls)." (PMID 26730404, 2015).